WNT7A (Wnt family member 7A)
Diseases named in the same sentence as WNT7A in open-access papers (continued):
Sharing a sentence is not in itself a finding about the gene and the disease.
breast carcinoma (10 papers, 2015 to 2025). "Consistent with our findings in mouse mammary tumours, in human breast cancers Wnt7a protein expression is predominantly associated with the tumour cell compartment, with lower levels detectable within the stroma." (PMID 26777421, 2016). "Most importantly, high Wnt7a expression is associated with reduced overall and metastasis-free breast cancer patient survival." (PMID 26777421, 2016). "The involvement of Wnt ligands in TGF-β–induced invasiveness has been previously reported for breast cancer cells, where Wnt7a and Wnt7b were found to be induced by the Smad3–JunB cooperative transcriptional activation." (PMID 38141763, 2024). "Two complementary approaches were taken to investigate the role of Wnt7a in promoting tumour aggressiveness of in vivo breast cancer models." (PMID 26777421, 2016). "Functionally, high Wnt7a expression in tumour cells promotes metastasis in vivo and, in human breast cancers, correlates with a desmoplastic, poor-prognosis stroma with high fibroblast TGFβ pathway activation and reduced patient survival." (PMID 26777421, 2016). "Similarly, EXO-transported Wnt7a increases the formation of breast cancer cell spheroids by activating the PI3K/Akt/mTOR signaling pathway, promoting fibroblast infiltration and angiogenesis, while the absence of Wnt7a significantly reduces angiogenesis." (PMID 40486870, 2025). "Additionally, Cav-1 and Wnt7a in EXOs released by breast cancer cells enhance tumor angiogenesis through different signaling pathways." (PMID 40486870, 2025). "In breast cancer, co-expression of Wnt ligands, including Wnt3, Wnt4, Wnt5a, and Wnt7a, leads to the activation of Wnt pathway, while in colorectal cancer, mutation or loss function of the APC gene or protein is more likely to be the reason for Wnt pathway activation." (PMID 29986466, 2018). "Importantly, in clinical breast cancer cohorts, tumour cell Wnt7a expression correlates with a desmoplastic, poor-prognosis stroma and poor patient outcome." (PMID 26777421, 2016). "To address the clinical significance of Wnt7a expression in tumours, we first examined whether Wnt7a expression in human breast cancer correlates with a desmoplastic stroma." (PMID 26777421, 2016). "E2F1 and E2F4 induce whereas pRb/RBL2 reduce WNT ligand expression (e.g. WNT7A, WNT7B, WNT10A, WNT4) thereby regulating self-renewal, chemoresistance and invasiveness of CSCs in both PDAC and breast cancer, and fibroblast proliferation." (PMID 38678032, 2024). "On the other hand, for UNB, specific upregulated DEGs included SMIM3, a leukemia promoter gene, WNT7A, a hypoxia induced EMT driver, PADI2, a tumorigenic breast cancer gene, and RAPGEF4, which modulates gliomas." (PMID 38538643, 2024).
gastric cancer (10 papers, 2019 to 2024). A primary or metastatic malignant neoplasm involving the stomach. "miRNA-127 can target the 3′-UTR region of WNT7A mRNA, reduce its expression, and inhibit the invasion and migration of gastric cancer cells." (PMID 38952556, 2024). "The WNT7A promoter was shown to be frequently methylated in gastric cancer, leading to its transcriptional downregulation." (PMID 36982422, 2023). "Overexpression of WNT7A in gastric cancer cells decreased the expression of the EMT markers Snail and Vimentin." (PMID 36982422, 2023). "For example, small inhibitory RNA (siRNA)-mediated knock-down of WNT7A has been shown to significantly inhibit migration and invasion of gastric cancer cells." (PMID 31847321, 2019). "Furthermore, reduced cell invasion, migration, and proliferation of gastric cancer cells were observed upon overexpression of WNT7A." (PMID 36982422, 2023). "Ambiguous roles have also been described for WNT7A in gastric cancer." (PMID 36982422, 2023). "In agreement with our results, the aberrant methylation of other genes involved in the Wnt signaling pathway (e.g., WNT5A and WNT7A) has previously been described in tumor cells from the BC luminal subtype and in other tumor types, such as gastric cancer or chronic lymphocytic leukemia." (PMID 36393855, 2022). "miR-127 suppresses gastric cancer cell migration and invasion via targeting Wnt7a." (PMID 32648571, 2020). "Interestingly, we could not detect the actin motor myosin 10 (MYO10), which regulates the formation and elongation of filopodia on WNT7A-positive dendritic filopodia, suggesting a difference from the Wnt8a cytonemes observed in zebrafish gastrulation or WNT3 cytonemes in human gastric cancer." (PMID 39576204, 2024).
bladder cancer (8 papers, 2015 to 2026). "On the other hand, Wnt7a was found highly expressed in the bladder cancer and pancreatic ductal adenocarcinoma, and Wnt7a overexpression in these two cancers not only promoted metastasis but also predicted poor prognosis." (PMID 31886205, 2019). "Additionally, miR-370-3p impeded bladder cancer cell invasion by suppressing Wnt7a expression, thus inhibited classical Wnt/β-catenin signal transduction and matrix metalloproteinase 10 (MMP10) levels." (PMID 35962353, 2022). "WNT7A depletion in 5637 HMI and T24 cells reduced urinary bladder cancer (UBC) cell invasion and decreased the levels of active β-catenin and its downstream target genes involved in ECM degradation, but these studies lacked detail on the regulatory mechanism between Wnt and ECM." (PMID 33665169, 2020).
glioma (8 papers, 2020 to 2025). A benign or malignant brain and spinal cord tumor that arises from glial cells (astrocytes, oligodendrocytes, ependymal cells). "In detail, WNT7A/B secretion by Olig2 + oligodendrocyte precursor-like glioma cells was observed to promote VCO and to be upregulated in response to anti-angiogenic treatment." (PMID 36691028, 2023). "CTBP1-AS2 regulates the epithelial-mesenchymal transition (EMT) of glioma by modulating the miR-370-3p/Wnt7a axis." (PMID 35039872, 2022). "Genes associated with the neuronal differentiation pathway (Pcsk9, Runx1, Cebpb, Fzd4, Wnt7a, Ascl1, Fzd2, Edn3, Olig2, and Gpc2), gliomas (Shc1, Cdk4, E2f2, and Ccnd1), and cell cycle (Bub1b, Bub, Ccnb1, Ccnb2, and Cdc20) were significantly downregulated." (PMID 36147849, 2022). "For CNS tumor, higher expression of WNT5A, lower expression of WNT7A and lower expression of WNT10B were found in glioma compared with NB tissues." (PMID 32181818, 2020). "While some studies have reported its upregulation in breast and colorectal cancers, suggesting a potential oncogenic function, others have reported its downregulation in glioma, where it acts as a tumor suppressor by targeting oncogenes such as CORO2A, APC2, WNT7A, and BOC." (PMID 40431607, 2025). "This could be due to residual levels of Wnt signaling within gliomas, as BBB-specific Wnt-ligands (Wnt7a, Wnt7b and Norrin) are expressed by glial lineage cell-types, including oligodendrocyte progenitors and astrocytes." (PMID 34425907, 2021). "WNT7A and WNT7B was shown to regulate glioma-vascular interactions." (PMID 32181818, 2020).
colorectal cancer (7 papers, 2015 to 2025). A primary or metastatic malignant neoplasm that affects the colon or rectum. "The lower the degree of differentiation, the higher the stage and the colorectal cancer with lymph node metastasis, the higher the positive rate of Wnt7a." (PMID 33791195, 2021). "To investigate the effect of Wnt7a on the proliferation of colorectal cancer cells, we first silenced Wnt7a in colon cancer cell lines HT29 and HT116." (PMID 33791195, 2021). "Currently, the studies on Wnt7a and colorectal cancer are still in the preliminary stage, so the study on its influence on the occurrence and development of colorectal cancer may provide a new idea for the diagnostic treatment of colorectal cancer." (PMID 33791195, 2021). "High expression of Wnt7a associated with poor prognosis and metastasis in PADC and could predict metastasis of colorectal cancer via EMT and poor prognosis." (PMID 34794402, 2021). "The expression of Wnt7a in colorectal cancer tissues and cell lines was analyzed, and the effect of Wnt7a on the proliferation of colorectal cancer cells was studied, so as to confirm the relationship between Wnt7a and the occurrence and development of colorectal cancer." (PMID 33791195, 2021). "After knockdown of Wnt7A, the proliferation rate of colorectal cancer cells was slowed down and the ability of clone formation was reduced, which proved that Wnt7A could promote the growth of colorectal cancer cells." (PMID 33791195, 2021). "In the present work, we analyzed the expression of Wnt7a in colorectal cancer tissues and cell lines, and studied the effect of Wnt7a on the proliferation of colorectal cancer cells, so as to confirm the relationship between Wnt7a and the occurrence and development of colorectal cancer." (PMID 33791195, 2021). "However, current studies on Wnt7a and colorectal cancer are few and preliminary." (PMID 33791195, 2021).
Stroke (6 papers, 2014 to 2025). Sudden impairment of blood flow to a part of the brain due to occlusion or rupture of an artery to the brain. "Western blot revealed Wnt7a level was increased in the Stroke + OPC group compared with the Stroke + PBS group (p < 0.05)." (PMID 31907363, 2020). "Interestingly, other studies have described the expression of Wnt7a following hypoxic conditions, indicating that the interplay of these signaling molecules might contribute to hypoxia-induced events, during pathological conditions such as stroke or cSVD." (PMID 38147228, 2024). "Among Wnt family members, Wnt7a appears to be critical during development and maintains the integrity of the BBB through Gpr124, during a stroke or in glioblastoma, as well as in homeostatic conditions." (PMID 32900826, 2020). "Regarding with signaling pathways, those expressed during embryogenesis such as FGF/FGFR, Notch, Shh, or Wnt7a/7b are not activated during post-stroke angiogenesis suggesting that post-stroke angiogenesis is not simply a recapitulation of developmental angiogenesis." (PMID 24672479, 2014).
hepatocellular carcinoma (5 papers, 2018 to 2025). A malignant tumor that arises from hepatocytes. "In order to understand the potential role of Wnt7a in hepatocellular carcinoma, we analysed the correlation between WNT7A RNA expression levels and overall survival in HCC." (PMID 31886205, 2019). "That meant Wnt7a might be a prognostic tool for hepatocellular carcinoma and more possibly affected the late stage." (PMID 31886205, 2019). "Then, we tried to illustrate how Wnt7a exerted its influence on hepatocellular carcinoma." (PMID 31886205, 2019). "In conclusion, Wnt7a, as an antioncogene in hepatocellular carcinoma, effectively regulated Wnt target genes that are important for HCC growth and progression." (PMID 31886205, 2019). "In hepatocellular carcinoma (HCC), WNT7A inhibits the adipogenesis of fibro-adipogenic progenitors (FAPs) by inducing the nuclear translocation of YAP independent of β-catenin." (PMID 39936032, 2025). "The secreted Wnt7a inactivated SKP2 leading to upregulation of P21, which inhibits the growth of hepatocellular carcinoma." (PMID 31886205, 2019). "But, to our knowledge, no research on the correlation between Wnt7a activity and hepatocellular carcinoma is reported now." (PMID 31886205, 2019). "Interest in the role of FZD9 in the lung was initiated by the discovery that FZD9 and Wnt7a induced non-canonical and tumor suppressive signaling in NSCLC cells, in contrast with studies in osteosarcoma and hepatocellular carcinoma." (PMID 35924166, 2022).
Al-Awadi/Raas-Rothschild/Schinzel phocomelia syndrome (4 papers, 2008 to 2025). "Although no WNT7A mutations were found in women bearing MDAs, homozygous WNT7A mutations are the known underlying cause of Al-Awadi/Raas-Rothschild/Schinzel phocomelia syndrome (OMIM 276820), which produces skeletal and Müllerian defects as well as occipital meningocele." (PMID 34160006, 2021). "In human, mutations in WNT7A cause a range of limb malformations including Fuhrmann syndrome and Al-Awadi/Raas-Rothschild/Schinzel Phocomelia syndrome, indicating the specific and conserved importance of WNT7A in multiple aspects of vertebrate limb development." (PMID 18538017, 2008).
cervical cancer (4 papers, 2015 to 2022). A primary or metastatic malignant neoplasm involving the cervix. "Because these authors found that WNT7A expression was also significantly reduced in cervical cancer samples, they restored WNT7A expression in HeLa cells, which resulted in a strong decrease in cell viability, proliferation, and migration." (PMID 26295406, 2015). "WNT7a was also found to decrease proliferation of cervical cancer cells." (PMID 35885035, 2022). "Furthermore, it was determined that Wnt7a was underexpressed in the cervical cancer cells and inhibited proliferation." (PMID 31886205, 2019).
Duchenne muscular dystrophy (4 papers, 2014 to 2024). Duchenne muscular dystrophy (DMD) is a neuromuscular disease characterized by rapidly progressive muscle weakness and wasting due to degeneration of skeletal, smooth and cardiac muscle. "Therapeutic potential of Wnt7a has indeed been tested in several systems, like the mouse model of Duchenne muscular dystrophy, where the Wnt7a treatment stimulated satellite cell expansion and myofiber hypertrophy and even led to a significant increase in muscle strength." (PMID 26056595, 2014). "Accordingly, therapeutic stimulation of WNT7a/FZD7 by injection of recombinant Wnt7a resulted in a significant increase in muscle strength and a reduce contractile damages in mdx mice (Duchenne Muscular Dystrophy (DMD) model)." (PMID 33466753, 2021). "Consequently, intramuscular injection of Wnt7a protein significantly ameliorates disease progression in mdx mice, a mouse model for Duchenne muscular dystrophy (DMD)." (PMID 39661666, 2024). "Injecting Wnt7a or p38, JAK/STAT inhibitors into the muscles can increase the number of satellite cells, muscle fiber size, and muscle strength in a Duchenne muscular dystrophy mouse model." (PMID 38428405, 2024).
esophageal cancer (4 papers, 2019 to 2022). A primary or metastatic malignant neoplasm involving the esophagus. "circRNA_001275 promotes cisplatin resistance by upregulating Wnt7a expression via competitively sponging miR-370-3p in esophageal cancer." (PMID 35646112, 2022). "CircRNA_001275 increased the wingless-type protein 7a (Wnt7a) expression by competitively sponging miR-370-3p to facilitate the resistance of DDP to esophageal cancer cells." (PMID 34537072, 2021). "One study found that Wnt ligand proteins (Wnt 1, Wnt2, and Wnt7A) were significantly upregulated in esophageal cancer, glioblastoma, and OC." (PMID 31462944, 2019). "It has been found that circRNA_001275 could contribute to DDP resistance in esophageal cancer through directly binding to and competitively sponging miR-370-3p to up-regulate Wnt family member 7A (Wnt7a) expression." (PMID 34881242, 2021).
Infertility (4 papers, 2014 to 2024). "Wnt7a-Cre PGRf/- mice were infertile due to defects in embryo attachment, stromal cell decidualization, the inability to cease estrogen-induced epithelial cell proliferation, and the lack of P4 regulated expression of its epithelial target genes." (PMID 26378916, 2015). "For examples, deficiency in the Wnt signaling, including in Wnt4, Wnt5a, and Wnt7a, will result in severe malformation of the genitals and infertility, whereas hyperactivation of the Wnt/β-catenin pathway can also lead to germ cell apoptosis and male infertility." (PMID 25188337, 2014). "Conditional knockout of Foxa2 or Wnt7a with PgrCre/+ mice leads to infertility with no signs of implantation." (PMID 39364135, 2024).
leukemia (4 papers, 2012 to 2024). A malignant (clonal) hematologic disorder, involving hematopoietic stem cells and characterized by the presence of primitive or atypical myeloid or lymphoid cells in the bone marrow and the blood. "In conclusion, we are demonstrating, by qRT-PCR analysis, that WNT7A is significantly reduced in leukemia-derived cell lines as well as in patients with leukemia when compared with clinically healthy volunteers." (PMID 22313908, 2012). "We were also able to demonstrate, in the Jurkat leukemia-derived cell line, that restoration of WNT7A (by lentiviral overexpression or the addition of human recombinant protein) inhibits cell proliferation." (PMID 22313908, 2012). "In summary, there is a statistically significant decreased expression of WNT7A, not only in leukemia-derived cell lines in comparison with the control group, but also in patients with ALL when compared with healthy volunteers." (PMID 22313908, 2012). "In conclusion, the experiments performed previously allow us to demonstrate quantitatively that leukemia-derived cell lines of both myeloid and lymphoid origins express very low levels of WNT7A." (PMID 22313908, 2012). "In this paper, we report the expression of WNT7A in normal peripheral T-lymphocytes and strongly reduced WNT7A expression, not only in leukemia-derived cell lines, but also in the peripheral blood cells of patients with leukemia." (PMID 22313908, 2012). "By restoring WNT7A expression in leukemia-derived cells, we were able to demonstrate that WNT7a inhibits cell growth." (PMID 22313908, 2012). "Because we found that WNT7A is expressed in CD3+ resting lymphocytes derived from healthy volunteers and not in immature leukemia-derived cells, it was in our interest to discern the biological effect of WNT7a restoration on leukemia cells." (PMID 22313908, 2012). "Ochoa-Hernandez AB demonstrated its role in leukemia, showing through the construction of overexpressing virus that Wnt7a is expressed in leukemia cell lines and Wnt7a expression in normal peripheral blood T lymphocytes is significantly higher than in leukemia cells." (PMID 33791195, 2021). "If this is true, therapeutic tools directed toward restoring WNT7A expression in patients with leukemia might increase the probabilities of their overcoming this disease." (PMID 22313908, 2012). "After demonstrating that WNT7A expression is strongly reduced in leukemia-derived cell lines, we wanted to determine whether WNT7A expression could also be diminished in blood samples of patients with leukemia in comparison with clinically healthy volunteers." (PMID 22313908, 2012). "However, there are limited numbers of studies regarding the role of WNT7a, both in normal and in leukemia-derived cells." (PMID 22313908, 2012). "Because WNT7A was expressed in resting peripheral T-lymphocytes, but severely reduced in activated T-lymphocytes, we assumed that leukemia-derived cell lines (which are undifferentiated and have a high grade of proliferation) should express low levels of this ligand." (PMID 22313908, 2012). "In addition to determining the expression of the WNT7A gene in blood cells, in leukemia-derived cell lines, and in samples of patients with leukemia, the aim of this study was to seek the effect of this gene in proliferation." (PMID 22313908, 2012). "WNT7a is mainly produced by CD3 T-lymphocytes, its expression decreases upon activation, and it is severely reduced in leukemia-derived cell lines, as well as in the blood samples of patients with ALL when compared with healthy controls (p ≤0.001)." (PMID 22313908, 2012). "To confirm that restoration of WNT7A inhibits cell growth in leukemia-derived cells, we modified K562, BJAB, and CEM cells to overexpress WNT7A employing an inducible-lentiviral expression system." (PMID 22313908, 2012). "Because we observed downmodulation of WNT7A in leukemia-derived cells, it appears that WNT7a in Jurkat cells does not activate the WNT/β-catenin pathway." (PMID 22313908, 2012).
leukemia (continued). "The finding that WNT7A restoration inhibits proliferation of leukemia-derived Jurkat cells, but not of PBMC, allows us to assume that WNT7A can be acting as a modulator of cell proliferation, especially in T-cells that are producing this protein." (PMID 22313908, 2012).